SPATA42 (spermatogenesis associated 42)
Synonyms: SRG7; AKNAD1-AS1
Gene: Long non-coding RNA gene on chromosome 1 (108,857,160 to 108,858,529, forward strand). Ensembl gene ENSG00000203897.
Diseases named in the same sentence as SPATA42 in open-access papers:
SPATA42 is named in the same sentence as 2 diseases in open-access papers, as found by Europe PMC text mining. Sharing a sentence is not in itself a finding about the gene and the disease.
SPATA42 shares sentences with these, for which no sentence is quoted: male infertility (2 papers); Azoospermia (1).